NFIL3 (nuclear factor, interleukin 3 regulated)
Diseases named in the same sentence as NFIL3 in open-access papers (continued):
Sharing a sentence is not in itself a finding about the gene and the disease.
cancer (continued). "We previously identified 32 rhythm genes and analyzed their expression alterations across cancers and revealed five rhythm genes, including nuclear factor interleukin 3 regulated (NFIL3), that were abnormally expressed in most of the detected cancer types." (PMID 35180863, 2022). "For the first time, we demonstrated that NFIL3 protein suppressed the transcription of NFIL3 gene, which explained the paradoxical expression pattern of NFIL3 at the mRNA and protein levels across cancers." (PMID 35180863, 2022). "NFIL3 promotes the progression of TNBC by suppressing NFKBIA transcription and then enhancing NF-κB signaling-mediated cancer-associated inflammation." (PMID 35180863, 2022). "We showed that pre-mRNA of NFIL3 was significantly downregulated upon increase of exogenous NFIL3 protein in all detected cancer cell lines." (PMID 35180863, 2022). "In recent years, several studies have shown that NFIL3 mediates chemotherapy resistance in choriocarcinoma cells and is often overexpressed in cancers with a poor prognosis." (PMID 31886210, 2019). "We also noticed that NFIL3 with high expression is featured in the worse-prognosis subtype and it regulates many cancer related genes." (PMID 27586240, 2016). "The second TF, NFIL3, restricts expression of certain FOXO targets and its expression in cancer is associated with patient survival." (PMID 25648588, 2014). "In cancer cells, NFIL3 was found to block FOXO1 access to cell death genes, potentially allowing FOXO1 to drive pro-oncogenic programs, a true paradigm shift for the PI3K pathway." (PMID 26539561, 2014). "In line with its ability to hinder cell death, NFIL3 has emerged as a novel survival factor in cancer." (PMID 26539561, 2014). "Recently, a host of novel roles have been identified for NFIL3 in immunological signal transduction, cancer, aging and metabolism." (PMID 26539561, 2014). "NFIL3 is emerging as a key signaling component in a myriad of cellular processes including metabolism, nerve regeneration, immune development and cancer." (PMID 26539561, 2014). "In an effort to provide a more comprehensive assessment of NFIL3 expression in cancer, we conducted a comparative analysis of NFIL3 mRNA expression across 34 cancer types, utilizing datasets from TCGA, TARGET, and GTEx, accessible through the UCSC Xena Browser." (PMID 38356719, 2024). "In addition, NFIL3 expression was evaluated in different cancer stages, and the NFIL3 expression level was significantly higher in the advanced stages of BLCA (p=0.0148) and HNSC (p=0.00489)." (PMID 38356719, 2024). "To confirm the contrary results regarding the aberrant expression of NFIL3 at the mRNA and protein levels in cancer, we detected the expression of NFIL3 at the protein level in four additional cancer types with NFIL3 mRNA downregulation, including LUSC, LUAD, CESC and OV, by performing IHC." (PMID 35180863, 2022). "However, it is frequently reported that the expression of NFIL3 is elevated in various cancer types." (PMID 35180863, 2022). "This study may not only elaborate the molecular mechanisms by which NFIL3 regulates cancer progression but also provide a new target for TNBC therapy." (PMID 35180863, 2022). "NFIL3 transcription factor is emerging as a key signaling component in a myriad of cellular processes, such as: metabolism, nerve regeneration, immune development and cancer." (PMID 26539561, 2014). "The full spectrum of NFIL3 regulated transcriptional programs in cancer have yet to be elucidated." (PMID 26539561, 2014). "Moreover, our results indicated that NFIL3 expression exhibited significant correlations with ImmuneScores in 23 cancer types, MicroenvironmentScores in 18 cancer types, and StromaScores in 19 cancer types." (PMID 38356719, 2024). "NFIL3 may be a novel biomarker with potential prognostic and immunotherapy roles in pan-cancer." (PMID 38356719, 2024).
cancer (continued). "To test this hypothesis, we exogenously overexpressed NFIL3 driven by CMV enhancer in two TNBC cell lines and an additional seven cancer cell lines representing six cancer types and detected the impact of elevated NFIL3 protein on the transcription of the endogenous NFIL3 gene." (PMID 35180863, 2022). "This discordance between NR1D1 and NR1D2 is a possible source of the small amplitudes in RRE-targets NPAS2, NFIL3, and CRY1 in the cancers." (PMID 40424435, 2025). "Our findings revealed a significant positive correlation between NFIL3 expression and TMB in various cancers, including LUAD, COAD, COADREAD, BRCA, KIPAN, and DLBC." (PMID 38356719, 2024). "Our analysis unveiled significant positive correlations between NFIL3 expression and MSI in specific cancers such as COAD, COADREAD, and LAML." (PMID 38356719, 2024). "Functionally, NFIL3 binds to and represses pro-apoptotic genes such as TRAIL to hinder the induction of apoptosis in cancer cells." (PMID 26539561, 2014). "In this study, we revealed that the expression of NFIL3 at the mRNA and protein levels was not coincident across cancers with an unclear mechanism." (PMID 35180863, 2022). "Moreover, CART, SIRT1, and PER2 negatively correlated with the infiltration of M2 cells show good prognosis of cancer patients, while SERPINE1 and NFIL3 positively correlated with the infiltration of M2 cells show poor prognosis of cancer patients." (PMID 31927791, 2020). "We revealed that NFIL3 could regulate the transcription of itself since it is a transcription repressor, thus it is possible that elevated NFIL3 protein reversely suppresses the transcription and causes the decrease of mRNA of NFIL3 gene in cancer tissues in a negative feedback manner." (PMID 31927791, 2020). "It will be critical to determine whether NFIL3 is required in DLBCLs that contain activated FOXO1 and the MLL-AF9 cancers in order to block the activation of cell death by FOXO factors." (PMID 26539561, 2014). "Delineating the full breadth of NFIL3 directed transcriptional programs such as those that counter FOXO and PAR transcription factors will be essential for understanding its contribution to cancer." (PMID 26539561, 2014). "However, the potential role of NFIL3 in human cancers has not been studied extensively." (PMID 38356719, 2024).
infection (6 papers, 2008 to 2023). The state of being infected such as from the introduction of a foreign agent such as serum, vaccine, antigenic substance or organism. "In grass carp, NFIL3 participates in host immunity against pathogen infection and can activate various gene expressions." (PMID 36593453, 2023). "This suggests that the requirement for NFIL3 can be overridden by cytokine signaling during infection." (PMID 25310240, 2014). "In the late stage of infection, NFIL3 was predicted as regulatory element of many DEG involved in the local as well as the systemic reaction." (PMID 20184744, 2010). "The early onset of this defense reaction is indicated by enhanced expression of NFIL3 already 6 h after infection." (PMID 20184744, 2010). "Furthermore, NFIL3 was found in infected quarters as 3.5-fold up-regulated DEG 24 h after infection." (PMID 20184744, 2010). "Interestingly, up-regulation of NFIL3 expression was found as soon as 6 h after infection." (PMID 20184744, 2010).
metabolic disease (4 papers, 2022 to 2024). A congenital disorder (due to inherited enzyme abnormality) or acquired (due to failure of a metabolically important organ) disorder resulting from an abnormal metabolic process. "Ultimately, our study findings will determine whether Nfil3 expression regulation, which is linked to both sex and diseases, could be the key to preventing and treating metabolic disorders." (PMID 39048678, 2024). "Enhancing hepatic NFIL3 activity in insulin-resistant conditions is advantageous for reducing glycaemic symptoms in metabolic disorders." (PMID 37559129, 2023). "We proposed the hypothesis that variations in GM composition and the associated BA metabolites play a significant role in the progression of SDs in metabolic disorders where Nfil3 is involved." (PMID 39048678, 2024). "Of particular interest is the absence of NFIL3 oscillation, which has been demonstrated to play an essential role in lipid handling and the progression of metabolic disease." (PMID 35600313, 2022).
bacterial infection (2 papers, 2014 to 2023). "Additionally, NFIL3 deficiency significantly reduces the intestinal innate immune response against acute bacterial infections such as Citrobacter rodentium and Clostridium difficile." (PMID 36593453, 2023).
cardiovascular diseases (1 paper, 2025). "Previous research revealed that NFIL3 plays a pivotal role in cardiovascular diseases and regulates the pathogenesis of HF, functioning as a survival mediator in the heart." (PMID 40933471, 2025).
infectious disease (1 paper, 2014). A disorder directly resulting from the presence and activity of a microbial, viral, or parasitic agent in humans. "Because of the general importance of ILCs in immune defense, NFIL3-dependent pathways may provide new targets for treatment of inflammatory and infectious diseases." (PMID 25310240, 2014).
NFIL3 also shares sentences with these, for which no sentence is quoted: heart failure (4 papers); colorectal cancer (3); Crohn disease (3); acute myeloid leukemia (2); Cognitive impairment (2); delirium (2); Hyperinsulinemia (2); status epilepticus (2); ulcerative colitis (2); 3-methylglutaconic aciduria (1); acute kidney injury (1); Allergy (1); bladder cancer (1); blood cancer (1); brain cancer (1); CACP) syndrome (1); cognitive decline (1); epilepsy (1); glioblastoma (1); heart diseases (1); hematopoietic cancers (1); Hepatitis B (1); Hepatitis C (1); invasive breast carcinoma (1); latent infection (1); legionellosis (1); leishmaniasis (1); leukemia (1); liver cancer (1); lymphocytic leukaemia (1).
A further 16 diseases each share a sentence with NFIL3 in 1 paper.